PLIN2 (perilipin 2)
Diseases named in the same sentence as PLIN2 in open-access papers (continued):
Sharing a sentence is not in itself a finding about the gene and the disease.
cancer (60 papers, 2012 to 2026). A tumor composed of atypical neoplastic, often pleomorphic cells that invade other tissues. "The study showed that cancer-associated fibroblasts release small particles called extracellular vesicles containing a protein called PLIN2." (PMID 41408408, 2025). "The underlying mechanisms by which PLIN2 is involved in these cancers include interacting with the cell cycle, ferroptosis, endoplasmic reticulum stress, reactive oxygen species, and so on." (PMID 39875372, 2025). "PLIN2 expression levels have been investigated as a potential diagnostic and prognostic marker in cancer." (PMID 38643120, 2024). "The accumulation of LDs has been recognized as a noticeable hallmark of ccRCC, and PLIN2 has been well studied in ccRCC to explore its biological role in cancer progression and its potential clinical application." (PMID 36439875, 2022). "Two studies from one group revealed that high PLIN2 mRNA expression is associated with a favorable cancer-specific survival in CC-RCC patients." (PMID 28404922, 2017). "Perilipin-2 is a lipid droplet protein that wraps around a neutral lipid core and is involved in lipid metabolism in many cells, and has also been found to be associated with cancer progression." (PMID 37828502, 2023). "Our findings provided mechanistic insights relevant for the exploitation of future Trip13 inhibitors for cancer therapy by defining Plin2 as predictive marker for the susceptibility of tumors to a respective targeted therapy in the context of a precision medicine approach." (PMID 36031387, 2022). "On the contrary, PLIN2 depletion significantly attenuated the proliferation of colon cancer cells, supporting the LD-associated proteins as potential druggable targets for cancer treatment." (PMID 33194695, 2020). "Conversely, the migration and invasion of cancer cells were diminished by macrophages with PLIN2 knockdown." (PMID 39921309, 2025). "Among all the DEGs, PLIN2 drew our attention resulting from its various functions in LDs biogenesis, metabolic diseases, neurological degenerative diseases, and cancers." (PMID 39875372, 2025). "IHC staining of samples from 96 CRC patients, staged according to the AJCC Cancer Staging Manual, 7th edition, showed that PLIN2 expression was higher in advanced CRC stages." (PMID 40640171, 2025). "Clusters 3 and 5 showed elevated expression of genes associated with cancer development and progression, such as CEBPB, PLIN2, PRDX1, PSMD6, and TXNRD1." (PMID 39805002, 2025). "In recent years, there has been increasing evidence linking PLIN2 to malignant tumors, including breast, liver, kidney, lung and oral cancer." (PMID 40640171, 2025). "Elevated PLIN2 expression has been in fact correlated with advanced tumor stage, lymph node metastasis, and reduced overall survival in some cancer types." (PMID 38643120, 2024). "For lipid storage, PLIN2 involved in transporting lipids into lipid droplets has been shown to be induced by HIF2α, which protects cancer cells from ER stress." (PMID 36750850, 2023). "The results of pan-cancer analysis in this study describe the expression levels of four genes (Irs2, Plin2, Pnpla2 and Srebf2) in various types of cancerous tissues compared to normal tissues." (PMID 37047411, 2023). "Currently, investigations into PLIN2 in several types of cancer have indicated that it has an important role in tumorigenesis." (PMID 35372038, 2022). "In particular, elevated circulating PLIN2 (cPLIN2) levels were found in plasma or urine of patients with some types of cancer (kidney, colorectal) with respect to healthy subjects." (PMID 33735111, 2021). "We further documented that in acidosis-adapted cancer cells, PLIN2 silencing using four siRNA duplexes designed to target distinct gene sites (Dharmacon) significantly reduced LD accumulation." (PMID 31974393, 2020).
cancer (continued). "Accordingly, perilipin-2 expression was increased in cancer cell lines under hypoxic conditions, as well as in the liver of mice treated with CoCl2, an inducer of hypoxia-like responses." (PMID 32029741, 2020). "We found that, among major members of the PLIN family, PLIN2 mRNA and protein expression was consistently increased in each of the tested 6.5/cancer cells while other PLIN isoforms remained unaltered." (PMID 31974393, 2020). "Based on the involvement of LDs in aggressive cancer phenotypes, we evaluated perilipin-2, which is a protein constituent of LDs, after treatment with mevalonate or cholesterol, by immunofluorescence and immunoblot analyses." (PMID 32751976, 2020). "Perilipin 2 is a LD membrane protein that is crucial for LD synthesis not only under normoxia, but also under conditions of hypoxia in cancer cells (route 14)." (PMID 27589734, 2016). "Besides, recent studies implied that the expression of PLIN2 changes in a variety of pathological conditions including cancer." (PMID 39875372, 2025). "Different cancers express altered levels of PLIN2 too, with a positive or negative association with overall survival depending on the type of cancer." (PMID 38650174, 2024). "PLIN2 is a marker of lipid droplets whose role in cancer has been controversial." (PMID 38779100, 2024). "Additionally, miR193a-CM upregulated genes for S100A8, AKR1C1, AREG, and PLIN2 were shown to inhibit angiogenesis and cancer growth." (PMID 36766731, 2023). "Regarding the lipid metabolism, an upregulation of FABP1 in HCC was shown to stimulate angiogenesis and cancer cell migration, while PLIN2 overexpression is observed in many cancers and is suggested to have a role in tumorigenesis, for example, by favoring adaptation to hypoxia." (PMID 36139435, 2022). "Detectable levels of circulating PLIN2 (cPLIN2) have been reported to be associated with some types of cancer, but no systematic analysis of age-related modifications in cPLIN2 levels has ever been performed." (PMID 33735111, 2021). "Finally, expression of PLIN2 that we found to be upregulated in acidosis-adapted cancer cells was inhibited upon TGF-β2 silencing." (PMID 31974393, 2020). "Increased expression of PLIN2 has been shown to favor the accumulation of LDs, contributing to a better control of the ER stress, to increase the protection against ROS, and to augment the resistance to therapeutic drugs in cancer cells." (PMID 33194695, 2020). "Moreover, at the level of mRNA expression PLIN2 (gene coding adipophilin) appears to be an outlier for virtually all tumor entities as summarized using cancer outlier profile analysis in the Oncomine database (see Supplementary Discussion 1)." (PMID 28404922, 2017). "Lipid droplets comprise an emerging target in a number of diseases, including cancer, and it has been suggested that the lipid droplet protein, PLIN2, might make an effective target." (PMID 28412757, 2017). "As with chronic irradiation, PPARβ/δ expression and activity were enhanced in the skin of wild-type animals upon acute UV exposure, especially in the epithelial compartment where carcinomas arise, as documented by the stimulation of two known target genes, Tgfβ1 and Plin2." (PMID 24203162, 2014). "To understand whether XBP1 has any role in regulating the lipid droplet content in skeletal muscle during cancer cachexia, we performed immunostaining for the Perilipin 2 protein, which is one of the most abundantly expressed lipid droplet-coating proteins in skeletal muscle." (PMID 40655023, 2025). "In addition, our group could demonstrate increased perilipin 2 amounts in a large variety of malignant tumors when compared to the respective normal tissues reminiscent of a Warburg effect." (PMID 36555099, 2022).
cancer (continued). "However, the described functional link of Trip13‐lipid metabolism and especially Plin2 in the regulation of mitosis, provides novel implications for cell biology as well as for the development of antimitotic treatment strategies against cancer." (PMID 36031387, 2022). "In addition to ccRCC and PCa, the involvement of PLIN2 in other cancers has also been detected." (PMID 36439875, 2022). "PLIN2 supports cell survival under hypoxic and metabolic stress, whereas SCD1 sustains cancer cell proliferation upon reoxygenation." (PMID 42292857, 2026). "According to the Genomics of Drug Sensitivity in Cancer (GDSC) and Cancer Therapeutics Response Portal (CTRP) databases, we selected the top four drugs negatively correlated with PLIN2, namely Z-LLNle-CHO, tozasertib, dabrafenib and CIL55." (PMID 41408408, 2025). "Other than simply participating in lipid storage, the perception of the perilipin 2 (PLIN2) role has been expanded to a series of metabolic diseases, neurodegenerative diseases, and cancers." (PMID 39875372, 2025). "Overexpression of PLIN2 and PLIN3 has been observed in a number of cancers and often correlates with higher cellular proliferation and poor prognosis." (PMID 39297796, 2024). "ACSL3, AIFM2, HSD17B7, LPCAT1, LSS, PLIN3 and RAB10 were up-regulated with the progression of cancer stage of HCC patients, while CIDEB, G0S2, HSD17B13, PLIN1 and PLIN2 were down-regulated." (PMID 37464334, 2023). "The comparison of proteins interacting with PLIN1 in adipocytes with those interacting with PLIN2 and ATGL in two cancer cell lines provides insight into the core components of LDs." (PMID 38130664, 2023). "The author revealed that the elevated expression of PLIN2 preserved the viability of ccRCC cells by decreasing UPR triggered by extra protein synthesis and maintaining ER homeostasis in cancer cells." (PMID 36439875, 2022). "In accordance with these findings, we found an increased expression of PLIN2 and HILPDA, and reduced levels of CPT1A transcripts in cancer tissue." (PMID 33322148, 2020). "The over-expression of PLIN2 has previously been reported for several cancer types, although its prognostic value is not clear." (PMID 31905780, 2019). "In addition, we found that SCD1 expression in cancer cells affects nonhistone protein deacetylation, whereas PLIN2 expression enhances protein acetylation." (PMID 42292857, 2026). "IMTGs are extremely dangerous for cancer and non-cancer patients; biochemically, IMTGs increased Plin-2 levels, a small molecule with epigenetic properties able to reduce muscle mass and strength, thus inducing mitochondrial dysfunction and autophagy in the muscle and resistance to anabolism." (PMID 39200115, 2024). "Perilipin 2 (PLIN2) and sterol O-acyltransferase 1 (SOAT1) are two proteins used to identify sebaceous glands in tissue sections while keratin 14 (KRT14) is useful for outlining the gland when investigating its involvement in cancer or for structural abnormalities." (PMID 30372477, 2018). "Furthermore, the expression of adipophilin (PLIN2), a specific marker for lipid droplet formation, was observed higher in HER2-positive and TNBC subtypes, but less in ER+PR+Ki67low and ER+PR+Ki67high subtypes, demonstrating its positive correlation with long-term cancer recurrence." (PMID 39333940, 2024). "They suggested that PLIN1, PLIN2, and PLIN3 may be involved in cancers such as hepatocellular adenoma and carcinoma, sebaceous adenoma and carcinoma, and lipoma tumors, while PLIN5 was excluded as not sufficient proof was given." (PMID 34067931, 2021). "Urinary perilipin 2 has been suggested as an early screening biomarker for RCC, which enables the differentiation between cancer patients and healthy controls, benign kidney tumours, noncancerous kidney diseases, and other cancers, including bladder and prostate cancers." (PMID 35328822, 2022).
infection (20 papers, 2009 to 2025). The state of being infected such as from the introduction of a foreign agent such as serum, vaccine, antigenic substance or organism. "Previously, at 36 and 72 hours post-infection two separate microarray analyses of C. burnetii-infected THP-1 cells reported upregulation of the LD coat protein-encoding gene plin-2." (PMID 29390006, 2018). "Our results identified the infection-mediated upregulation of genes encoding lipid droplet-associated molecules, including anti-lipolytic HCAR2, perilipin -2 and -3, which regulate lipid droplet formation and degradation and HILPDA." (PMID 35531332, 2022). "Using immunofluorescence and western blotting analysis, we observed that PLIN2 increased after infection or AHL-12 treatment." (PMID 34083514, 2021). "The released PPARG accelerates LDs degradation and AHL-12 prolongs the survival of host cells in infection via binding PLIN2." (PMID 34083514, 2021). "Consistent with previous studies in mammals, the number and size of LDs as well as the expression of LDs marker protein PLIN2, were significantly induced upon infection with live and killed V. harveyi, confirming the induction of V. harveyi on the LDs accumulation." (PMID 40417253, 2025). "PLIN2 protein were significantly decreased at 8 h and 12 h after EV-A71 infection." (PMID 36246276, 2022). "Using immunofluorescence, we noticed that PPARG was redistributed from nuclei to cytoplasm and colocalized with PLIN2 after infection or AHL-12 treatment, and the redistribution could be weakened by silencing Tas2r138." (PMID 34083514, 2021). "Furthermore, qPCR analysis revealed that H19 overexpression in hepatocytes led to the increased expression of numerous genes involved in lipid synthesis and storage, such as Gpam, Mogat, Fasn, Acaca, Apoc3, Srebp, Plin2, Plin3, Lipe and Mlxipl at 72 hours after Ad‐H19 infection." (PMID 31809000, 2020). "(A) Seahorse flux analyses of scramble or Plin2-/-, Slc27a1-/-, and Cpt2-/- macrophages infected with Mtb Erdman strain at a multiplicity of infection (MOI) of 1 24 hours post infection." (PMID 40080408, 2025). "We used the Venus protein as an internal control to monitor infection efficiency since the expression system uses an internal ribosome entry site (IRES), therefore, mRNA expression of Venus reflects that of Plin2." (PMID 26876687, 2016). "After a 4-day infection with WT H37Rv, Rv3378c-mutant strains, or Rv3378c-complemented strains, macrophages lacked consistent changes in the appearance or number of PLIN2+ LDs." (PMID 36757797, 2023). "The expression of Plin2 and Cd36 was also increased by VACV infection, in line with the results of the proteomic analysis, further supporting an increase in lipid uptake and storage during infection." (PMID 36453897, 2022). "These include perilipin 2 (PLIN2), which was increased subsequent to primary infection by E. acervulina and E. maxima, as well as prostaglandin reductase 1 (PTGR1), CD36, and carnitine O-octanoyltransferase (CROT), which were decreased following E. acervulina primary infection." (PMID 22140460, 2011). "Interestingly, deletion of Plin2 did not inhibit LD formation, as BMDM derived from Plin2-/- mice did not have a defect in LD accumulation during M. tuberculosis infection with IFN-γ activation at either 1 or 3 days post-infection." (PMID 29370315, 2018).
metabolic disease (14 papers, 2013 to 2025). A congenital disorder (due to inherited enzyme abnormality) or acquired (due to failure of a metabolically important organ) disorder resulting from an abnormal metabolic process. "Given the described associations with multiple systemic, age-related and metabolic diseases, it is tempting to speculate that PLIN2 may reflect metabolic dysregulation and a moribund state in critical illness." (PMID 34572396, 2021). "Other studies have indicated that PLIN2 expression is correlated with metabolic disorders, Type 2 diabetes, and hepatic steatosis." (PMID 38650174, 2024). "PLIN-2 is involved in the storage of neutral lipids in lipid droplets and its increase has been observed in many metabolic diseases." (PMID 36135761, 2022). "Encouraged by data highlighting the role of PLIN2 in the pathophysiology of age-related and metabolic diseases, we performed subgroup survival time analyses." (PMID 34572396, 2021). "PLIN2 dysregulation is involved in many metabolic disorders and age‐related diseases." (PMID 38650174, 2024).
kidney disease (3 papers, 2022 to 2024). "Protein levels of SCAP, FASN, PLIN2, NLRP3, and GSDMD were higher in fibrotic human kidney tissue samples, likely indicating that DNL could be associated with kidney disease." (PMID 38051585, 2023). "Healthy controls and kidney disease samples showed strong expression of DNL genes, including ACSS2, NR1H3 (liver X receptor α [LXRA]), NR1H4 (farnesoid X receptor [FXR]), SREBF1, SCAP, PLIN2, PLIN5, ACACAB, ATP citrate lyase (ACLY), and FASN in PT cells and some other tubule cells." (PMID 38051585, 2023).
inflammation (1 paper, 2018). Aberrant reaction of the microcirculation characterized by movement of fluid and leukocytes from the blood into extravascular tissues. "Recent studies have shown that PLIN2-deficient mice, without any truncated protein products, can be protected against adipose inflammation." (PMID 29723991, 2018).
skin disorder (1 paper, 2025). Any deviation from the normal structure or function of the skin or subcutaneous tissue that is manifested by a characteristic set of symptoms and signs. "Despite their expression in the epidermis, mutations in either PLIN2 or PLIN3 have not been linked to Mendelian skin disorder in humans so far." (PMID 40818613, 2025).
PLIN2 also shares sentences with these, for which no sentence is quoted: retinal degeneration (11 papers); cardiovascular disease (5); autosomal dominant retinitis pigmentosa (4); liver cancer (4); diabetic nephropathy (3); liver (3); night blindness (3); adenocarcinoma (2); breast tumor (2); chronic hepatitis C (2); dementia (2); fibrosis (2); kidney cancer (2); leprosy (2); liver cirrhosis (2); pancreatic cancer (2); retinopathy (2); viral infection (2); adenoid cystic carcinoma (1); age-related macular degeneration (1); alcohol abuse (1); autosomal dominant centronuclear myopathy (1); Bardet-Biedl syndrome (1); basal cell carcinoma (1); Cerebral ischemia (1); chronic myelogenous leukemia (1); chronic obstructive pulmonary disease (1); combined immunodeficiency (1); cone-rod dystrophy (1); coronary artery disease (1).
A further 61 diseases each share a sentence with PLIN2 in 1 paper.